NKX2-1 (NK2 homeobox 1)
Diseases named in the same sentence as NKX2-1 in open-access papers (continued):
Sharing a sentence is not in itself a finding about the gene and the disease.
tumor (continued). "From these data, we infer that C1 represents tumor cells that are phenotypically NKX2-1-positive." (PMID 30475207, 2018). "By identifying the mechanisms through which NKX2–1 operate in the subpallial telencephalon we might also learn more about its enigmatic role in tumor biology." (PMID 30217225, 2018). "Next, we assessed whether PD‐L1 is expressed in NKX2‐1‐expressing tumor cells in human NSCLC specimens (Dataset EV1)." (PMID 28255028, 2017). "Among the NKX2‐1‐positive tumor cases, 29% (20 out of 68) expressed PD‐L1." (PMID 28255028, 2017). "NKX2-1 has both oncogenic and tumor-suppressor functions depending on the cell context." (PMID 26871466, 2016). "However, haploinsufficiency of NKX2-1 enhanced KrasG12D-mediated tumour progression, but reduced EGFRL858R-mediated progression in transgenic mice model." (PMID 25881545, 2015). "This likely reflects the heterogeneity among different patient’s tumors, where distinct cell types of origin, differentiation patterns, and/or tumor (epi)genetic alterations may influence the landscape of genes regulated by NKX2-1." (PMID 26556242, 2015). "Nkx2-1 regulation of lung cell proliferation and survival was previously shown in development and tumor cell lines, but the effector genes directly regulated by Nkx2-1 were largely unknown." (PMID 22242187, 2012). "In neuroendocrine prostate cancer, NKX2-1 acts as a key transcriptional driver that upregulates serine/glycine synthesis enzymes, thereby reprogramming cellular metabolism to support proliferation, invasion, and overall tumor aggressiveness under nutrient‐limited conditions." (PMID 40297177, 2025). "However, the involvement of NKX2‐1 in modeling the tumor immune microenvironment is still unclear." (PMID 39113226, 2024). "Targeted oncogene activation using Nkx2-1 as Cre driver might thus potentially uncover organotypic features of tumor development related to spatiotemporally different expression patterns in thyroid and lung, respectively, which come into place embryonically and maintain in adulthood." (PMID 37534159, 2023). "Interestingly, the maintenance of tumor histopathology was compromised by localized s.c. injection of the ASC and AC cells, with transplant-derived lesions exhibiting stromal infiltration and loss of the AC marker nkx2-1." (PMID 36355420, 2022). "For example, the lung cancer lineage specifiers SOX2 and NKX2-1 contribute to tumor cell fate and neutrophil recruitment, suggesting that the determination of tumor immune microenvironment might impact the nature of the tumor." (PMID 34497681, 2021). "Additionally, in-depth molecular-level investigations have demonstrated that CDX2 can reduce the expression of downstream target genes, including axis inhibition protein 2 (AXIN2) and lung lineage transcription factor Nkx2-1, which subsequently inhibit tumour invasion and metastasis." (PMID 29179508, 2017). "We elucidated the transcription factor–target gene regulatory network involving NKX2-1 and TEAD1 in malignant tumor cells derived from AT2 cells." (PMID 41415280, 2025). "NKX2-1 (NK2 Homeobox 1; TTF-1) is a lineage transcription factor frequently amplified or overexpressed in LUAD; such gain sustains epithelial identity and tumor fitness." (PMID 41154602, 2025). "Similar to lineage‐defining factors like NKX2‐1 and SOX2, tumour lineage is governed by binary epigenetic regulation." (PMID 40847555, 2025). "Intrinsically, the tumor-driving factors SOX2 and NKX2–1 have opposing regulatory effects on TAN accumulation, suggesting that cancer cell intrinsic factors also shape TIME, challenging the notion that tissue type alone determines TIME." (PMID 40568576, 2025).
tumor (continued). "Altogether, our results demonstrate that low expression of NKX2‐1 fosters tumor growth, and targeting the CXCLs/CXCR2 axis with SB225002 mitigates the tumor growth induced by NKX2‐1 downregulation." (PMID 39113226, 2024). "Here, we showed that the reduced expression of NKX2‐1 activated CXCLs/CXCR2 signaling, and targeting this pathway resulted in reduced tumor growth." (PMID 39113226, 2024). "We next compared tumours from the SCC and ADC subtypes, as determined by keratin 5 (Krt5), thyroid transcription factor 1 (Ttf-1/Nkx2-1) and Usp28 staining, in KPL mice." (PMID 37202505, 2023). "NKX2-1 and CK7 signals were downregulated, while altered expression of the p63 isoform and upregulated SOX2 were detected in KPU tumor lysates." (PMID 38093367, 2023). "Focally deleted regions identified the tumour-suppressor genes RHOA at 3p21, CDKN2A and CDKN2B at 9p21, RAD51B, MAX, DICER1, BCL11B, NKX2-1, CCNB1IP1 and BAZ1A at 9q33." (PMID 34980126, 2022). "Although three recent papers reported three unusual cases of NSCLC with co-expression of TTF1 (NKX2-1) and p40 (TP63) in the same cells by IHC staining, they failed to observe the molecular heterogeneity present in an individual tumor." (PMID 35962452, 2022). "For patients P10 and P11, the staining results also showed the presence of NKX2-1 and TP63 double-positive cells in tumor tissues." (PMID 35962452, 2022). "In normal and tumor lung tissue, high NKX2-1 levels activate SFTP synthesis, but high TGF-β1 levels inhibit NKX2-1, leading to low SFTP expression." (PMID 35081981, 2022). "NKX2-1 and KLF4 can act as oncogenes or tumor suppressors depending on the type of tissue and the microenvironment." (PMID 35081981, 2022). "Both Pepsinogen C and POU2F3-positive cells were found in alveolar hyperplasia induced by Nkx2-1 deletion, consistent with the microscopic similarity between these hyperplasia and residual MAPKi-treated BPN tumor cells." (PMID 33821796, 2021). "In both NKX2-1-positive and NKX2-1-negative tumors, combined BRAF/MEK inhibition leads to substantial tumor regression, but drug-tolerant cells persist with the potential to relapse." (PMID 33821796, 2021). "Chromatin immunoprecipitation-RNA sequencing analyses on a set of murine LUSC and LUAD tumours, suggested that SOX2 and NKX2-1 exert antagonistic effects on the regulation of Cxcl5 expression." (PMID 34354223, 2021). "In human papillomavirus infected cervical cancer, MZF1 induces the expression of another transcription factor, NKX2-1, which in turn upregulates a cancer stem cell regulator FOXM1, resulting in increased tumor growth and invasion." (PMID 31963147, 2020). "In lung cancer, MZF1 can upregulate the expression of NKX2-1, which in turn increases the expression of FOXM1 resulting in facilitated tumor growth and invasion." (PMID 31963147, 2020). "Dividing tumor cells into classes representing NKX2−1 ± and SFTPA +/- (for definitions) shows significant effects (chi-squared p<0.001) of tumor genotype on co-expression of NKX2-1 and SFTPA." (PMID 31452510, 2019). "PDCD4, NKX2-1 and PRKAA1 (AMPKA1) are well known tumor supressor genes, and our result suggests that DTL downregulates these genes." (PMID 28336923, 2017). "We found significant cis-eQTL of genes near NRG1, NKX2-1, DIRC3, PCNXL2 and VAV3 in the normal and tumour thyroid tissue." (PMID 28703219, 2017). "Among the 10 amplification-based oncogenes, we identified that six genes (MDM2, MYC, MYCL, MYCN, NKX2-1, and SKP2) were amplified and overexpressed in ≥10 tumor samples." (PMID 28377632, 2017). "The tumor tissues were further confirmed by immunohistochemical assessments, which showed that thyroid transcription factor 1 (TTF-1 or NKX2–1) and Cytokeratin 7 (CK7) were all significant positive." (PMID 25474437, 2014). "NKX2-1/FOXA2 further recruits p300/CBP to activate NE enhancers, and pharmacological inhibition of p300/CBP effectively blunts NE gene expression and abolishes NEPC tumor growth." (PMID 40691407, 2025).
tumor (continued). "Nuclear NKX2-1 expression was partially detected; however, no p40 expression was observed in the primary tumor." (PMID 38829559, 2024). "NKX2-1, also known as TTF-1, is a lineage-specific transcription factor involved in the occurrence of lung cancer and regulate the adeno-to-squamous transdifferentiation to determined tumor phenotype." (PMID 38708353, 2024). "NKX2-1 was significantly more abundantly expressed in LUADs compared with LUCSs and LCNECs in tumor micro-regions, and slightly, yet not significantly, more in LUAD HLA-II+ tumors (samples 03421 and 02672)." (PMID 37127787, 2023). "Moreover, we confirmed that NKX2-1 and TP63 were coexpressed in the same tumor cells by RNA in situ hybridization." (PMID 35962452, 2022). "BRAF/MEK inhibitors drived NKX2-1 positive tumor cells into a stationary state, while NKX2-1 negative cells cannot exit the cell cycle after the same treatment." (PMID 36703749, 2022). "Our data show that the level of MAPK pathway activity dictates the specific identity adopted by NKX2-1-negative tumor cells within the gastric lineage." (PMID 33821796, 2021). "Furthermore, NKX2‐1/TTF‐1 shows different functions depending on cell conditions, being considered a double‐sword gene with lineage‐dependent tumour cell survival and tumour suppression activities depending on the context." (PMID 34014042, 2021). "In the validation set, 62 tumours (9.3%) showed no expression of NKX2‐1/TTF‐1 exon 1; such tumours were significantly associated with older age, EGFR wild‐type tumours, and poor prognosis." (PMID 34014042, 2021). "Based on these grading criteria, we found that high-grade BPN tumors comprised a much greater proportion of the NKX2-1-negative tumor burden than low-grade BPN tumors (~74% vs. 26%)." (PMID 33821796, 2021). "Whereas BRAF/MEK inhibitors drive NKX2-1-positive tumor cells into quiescence, NKX2-1-negative cells fail to exit the cell cycle after the same therapy." (PMID 33821796, 2021). "LADs with no expression of NKX2‐1/TTF‐1 exon 1 were significantly associated with older age (p = 0.0006), no TTF‐1 immunoreactivity (p = 0.0009), and EGFR wild‐type tumours (p = 0.0009)." (PMID 34014042, 2021). "This list included NKX2-1 and TBX4, both of which have tumor suppressor functions." (PMID 33083012, 2020). "Besides NKX2-1, we identified that HNF1B, a previously reported tumor suppressor found in other cancer types, STAT6, and SP100 were inactivated and linked to many silenced enhancers in a subgroup of LUAD." (PMID 32925947, 2020). "Notably reduced expression of AT2 markers begins early in tumor development and occurs despite sustained NKX2-1, FOXA1, and FOXA2 expression in tumor cells." (PMID 31452510, 2019). "Concomitant Foxa1/2 deletion at initiation reverses this phenotype, showing that when FoxA1/2 are absent at tumor initiation, NKX2-1-negative lesions equilibrate to a low proliferation state that never progresses to macroscopic disease." (PMID 30475207, 2018). "When Nkx2-1, Foxa1 and Foxa2 are deleted at tumor initiation, the resulting lung lesions lacked evidence of either pulmonary or gastric differentiation." (PMID 30475207, 2018). "In the absence of FoxA1/2 activity, NKX2-1-negative tumor cells adopt a more proximal cell fate with features of either the transitional epithelium of the SCJ or the squamous epithelium of the forestomach/esophagus, depending on the context of FoxA1/2 loss." (PMID 30475207, 2018). "In NKX2-1 negative mice models with KRAS mutations, reduced tumor volume was seen when TTF-1 expression was induced." (PMID 25594059, 2014). "Hence, understanding HNF4α’s role in NKX2-1-positive LUAD and its molecular relationship with NKX2-1 could greatly help characterize lineage plasticity and tumor progression in LUAD." (PMID 40707360, 2025).
tumor (continued). "Interestingly, there was no significantly difference in NKX2-1 expression between normal and tumor tissues in LUAD." (PMID 38708353, 2024). "Yet, NKX2–1 tumours do not show altered endothelial CD31/PECAM-1 staining patterns." (PMID 36932191, 2023). "Moreover, pathologic examination of H&E stained tumours, revealed severe bleedings and necrosis in the lungs infiltrated by NKX2–1 tumours, but not in vector control tumours, highlighting a more aggressive phenotype of NKX2–1 tumours." (PMID 36932191, 2023). "In the absence of NKX2-1, residual tumor cells fail to exit the cell cycle." (PMID 33821796, 2021). "In this model, haploinsufficiency of NKX2-1 slowed tumor progression rather than enhancing it." (PMID 31452510, 2019). "Among the NKX2‐1‐negative tumor cases, only 12% (nine out of 72) expressed PD‐L1." (PMID 28255028, 2017). "In addition, patients whose tumour exhibited no expression of NKX2‐1/TTF‐1 exon 1 had significantly shorter median OS (log‐rank test, p = 0.0306; Breslow–Wilcoxon test, p = 0.0032); however, these differences were barely significant compared to TTF‐1 protein expression." (PMID 34014042, 2021). "We identify NKX2-1 and TBX4 inactivation as early tumor suppressor events in normal non-ciliated lung epithelial cells from smokers." (PMID 33083012, 2020). "Napsin (NAPSA) was expressed in only one of the 2 AC, while TTF1 (NKX2-1) was strongly expressed in one AC, and expressed at lower levels in one ASC line, neither of these tumor markers was present in the stroma." (PMID 24324581, 2013). "Interestingly, immunohistochemical (IHC) end-point analyses revealed that independent of the tumor source (KL;ASC versus KL;AC), resulting s.c. tumors did not exhibit staining for the AC biomarker nkx2-1." (PMID 36355420, 2022). "Nevertheless, it was demonstrated that no expression of NKX2‐1/TTF‐1 exon 1 was frequently detected in EGFR and KRAS wild‐type tumours, suggesting that a tumour suppressive role of NKX2‐1_004 might be independent of such oncogenic alterations." (PMID 34014042, 2021). "Interestingly, these transcripts were not elevated in Nkx2-1 deleted KRAS-driven tumor cells and decreased cAMP-dependent PKA activity may be one reason why tumor initiation is impaired in BPN tumors." (PMID 33821796, 2021). "Furthermore, analysis of histopathology and NKX2-1 and tumor protein 63 (p63) biomarker expression to respectively depict ADC and SCC tissue, showed that constitutive absence of EphA3 did not alter the tumor histology." (PMID 25713296, 2015).
cancer (84 papers, 2008 to 2026). A tumor composed of atypical neoplastic, often pleomorphic cells that invade other tissues. "In summary, the clinical data, cellular models, and animal experiments demonstrated that low expression of NKX2‐1 was associated with features related to advanced cancer status and worse clinical outcomes." (PMID 39113226, 2024). "In this work, we identify NKX2–1 as a transcription factor driving the overexpression of serine/glycine synthesis enzymes and causing cell addiction to this pathway in cancer." (PMID 36932191, 2023). "On the other hand, NKX2–1 expression is also associated with a favorable prognosis in affected patients, due to its capacity to attenuate the invasive capacity of carcinomas." (PMID 30217225, 2018). "CEH-24 is a conserved NK2 class homeodomain protein that is homologous to mammalian NKX2-1, whose mutation leads to cancer cell survival and progression in humans." (PMID 28244369, 2017). "Next, we explored whether the NKX2–1-driven increased expression of serine/glycine synthesis enzymes causes metabolic rewiring of cancer cells." (PMID 36932191, 2023). "CD274/PD-L1 that is induced by NKX2-1 has been a hallmark of cancer immunotherapy along with its receptor PD-1 (also known as PDCD1), which can be targeted by therapeutic antibodies that activate anti-tumorigenic T cells by blocking the interaction between CD274/PD-L1 and PDCD1/PD-131." (PMID 33980985, 2021). "Additionally, the expression of the lung cancer associated transcription factor, NKX2-1, is highly correlated with its methylation and also clusters with several other lung- associated genes, for example, SFTA3 and SOX2, at the PTM level." (PMID 28994825, 2017). "In AR-overexpressing NPC-B13 cells, AR appeared to regulate thyroid transcription factor-1 (TTF-1, encoded by NKX2-1 gene) and its downstream target epidermal growth factor receptor (EGFR), thereby promoting cancer cell proliferation." (PMID 41633021, 2026). "In summary, our findings suggest that low expression of NKX2‐1 stimulates specific phenotypic properties in neutrophils, which potentially contribute to increased cancer progression through cell communication and cell proliferation." (PMID 39113226, 2024). "Altogether, our scRNA‐seq analysis demonstrated that the knockdown of NKX2‐1 promoted the infiltration of the neutrophil population with cancer‐promoting properties." (PMID 39113226, 2024). "In this manuscript, we highlight altered serine/glycine metabolism as key target in NKX2–1-driven cancers to improve current treatment regimens." (PMID 36932191, 2023). "To confirm these findings, we transduced DND41 T-ALL and A549 LUAD cancer cell lines with an NKX2–1 overexpression vector." (PMID 36932191, 2023). "We reported recurrent methylation changes in the promoters of several genes, many previously implicated in cancer, including FAM83A and SEPT9 (hypomethylation), as well as PCDH7, NKX2-1, and SOX17 (hypermethylation)." (PMID 37742993, 2023). "Further characterisation by metabolic profiling and in vivo experiments identify NKX2–1 as a novel oncogenic driver of serine/glycine synthesis addiction in cancer." (PMID 36932191, 2023). "In conclusion, NKX2–1 overexpression alters both the lipidome and epigenetic landscape of cancer cells." (PMID 36932191, 2023). "NcORFs from differentially expressed cancer genes include an out-of-frame ncORFs from NKX2-1 with a CNIT score of 0.8." (PMID 37275273, 2023). "Collectively, we identify NKX2–1 as a novel transcriptional regulator of serine/glycine synthesis addiction across cancers, revealing a therapeutic vulnerability of NKX2–1-driven cancers." (PMID 36932191, 2023). "Surprisingly, we found that many cancer cells from P11 not only coexpressed NKX2-1 and TP63 but also showed high expression of CHGB and UCHL1, which are markers of neuroendocrine cells." (PMID 35962452, 2022).